AR (androgen receptor)
Diseases named in the same sentence as AR in open-access papers (continued):
Sharing a sentence is not in itself a finding about the gene and the disease.
prostate carcinoma (continued). "In conclusion, our findings highlight novel consequences of constitutively active AR variants on the regulation of mesenchymal markers in prostate cancer." (PMID 23658830, 2013). "Increases of AR expression and activity have been well documented to be associated with prostate cancer development and CRPC." (PMID 23951060, 2013). "Of those, miR-34a and miR-34c expression was negatively associated with AR levels based on analysis of clinical prostate cancers." (PMID 23896594, 2013). "Evidence strongly supports a role for androgens and AR CAGn in prostate cancer (PC) risk and progression." (PMID 23467468, 2013). "The findings presented in the current study expand upon our previous work describing the association of phosphorylated serine 213 in prostate cancer tumours and demonstrate that phosphorylation of AR can positively and negatively regulate AR actions." (PMID 23945560, 2013). "E2F1 is a direct activator of the AR promoter, and loss of RB is associated with increased AR levels and progression of prostate cancers to castration resistance." (PMID 23902736, 2013). "Recently, it was shown that mutation of the AR is sufficient for causing prostate cancer development and progression and that overexpression of AR converts prostate cancer growth from androgen-dependent to androgen-independent." (PMID 23724033, 2013). "The short tandem repeat in exon 1 of the androgen receptor gene widely studied in association with prostate cancer is slightly but significantly shorter in intellectually gifted boys." (PMID 23382957, 2013). "Such mutations of the AR gene have been identified in the LNCaP cell line, which has been associated with recurrence of prostate cancer." (PMID 24282788, 2013). "Conversely, shorter AR polyglutamine tracts and thus a more transcriptionally active AR have been associated with prostate cancer or premature pubarche." (PMID 23599814, 2013). "Inheritance patterns also support a contribution of X-linked genes (which include the AR), with brothers of individuals succumbing to the disease showing greater risk of developing prostate cancer themselves than sons of individuals with the disease." (PMID 23467468, 2013). "PTPN1 appeared as a good candidate since it has previously been implicated with the progression of prostate cancer along with evidence that the androgen receptor is a transcriptional regulator of PTPN1." (PMID 23372565, 2013). "HSP-90 is another multifaceted molecular chaperone implicated in the progression of prostate cancer by the induction of several upstream signaling pathways, which promote aberrant androgen receptor activation and stabilize the androgen receptor protein." (PMID 23819055, 2013). "Pathway analysis of these networks has implicated the AR in the regulation of metabolism and endoplasmic reticulum (ER) stress response in prostate cancer cells." (PMID 23724116, 2013). "For instance, overexpression of the potassium channel TREK-1, the androgen receptor, and cyclin D1 have each been implicated in increased proliferation in prostate cancer cells." (PMID 23990931, 2013). "This leads to the formation of multiprotein complexes involved in the AR mediated transcriptional regulation of various genes implicated in prostate cancer growth and proliferation." (PMID 23819055, 2013). "Based on gene microarray studies of seven different human prostate cancer xenograft models, the increase of AR mRNA is the only change consistently associated with the development of the castration-resistant prostate cancers." (PMID 24349321, 2013). "The development of lethal, castration resistant prostate cancer is associated with adaptive changes to the androgen receptor (AR), including the emergence of mutant receptors and truncated, constitutively active AR variants." (PMID 23674566, 2013).
prostate carcinoma (continued). "Prostate cancer (PCa) is currently a leading cause of morbidity in the western male population, and it is known that the androgen receptor (AR) plays a central role in the development and progression of this tumor." (PMID 24236111, 2013). "AR and PKARIα are implicated in the activation of AR signaling and progression of prostate cancer towards castration resistance." (PMID 23736698, 2013). "Veldscholte and colleagues discovered that androgen-dependent human prostate cancer LNCaP cells harbor the AR with single missense mutation on ligand-binding lesions (Thr877Ala)." (PMID 23896594, 2013). "There are other pre-RC components, such as Orc2, Cdt1, and Mcm7, that are also reported to be associated with AR in prostate cancer cells." (PMID 23437213, 2013). "Prostate cancer is the second most common cause of cancer-associated deaths in men and signalling via a transcription factor called androgen receptor (AR) is an important driver of the disease." (PMID 23724116, 2013). "Of them, mutation, amplification, and expression alternative-splice variants of the androgen receptor are related to the adaptation of recurrent prostate cancer to low levels of androgen during androgen-deprivation therapy." (PMID 23041906, 2012). "The main genetic determinant of AGA is the androgen receptor (AR) and prostate cancer susceptibility loci identified through recent GWA studies overlap with androgen receptor binding sites demonstrating a shared etiologic factor in these two conditions." (PMID 22693459, 2012). "Specifically, reciprocal interactions between the AKT/mTOR and AR pathways have been implicated in prostate cancer progression." (PMID 22614157, 2012). "In prostate cancer, one of the most clinically relevant examples of differential expression of isoform variants has only recently been characterized for the androgen receptor (AR)." (PMID 22956952, 2012). "Likely, mechanisms that underpin initiation and progression of prostate cancer so far proposed include AR mutations, allowing receptors to be activated by new ligands." (PMID 23181808, 2012). "In an unrelated study, PCR based analysis of prostate cancer CTCs detected several AR mutations some of which have been associated with therapeutic resistance to anti-androgen therapy." (PMID 23087897, 2012). "AR dysfunction is associated with a wide variety of pathologies including prostate cancer, type 1 diabetes and metabolic disorders, such as type 2 diabetes." (PMID 23071669, 2012). "Another recent study also found a novel human AR splice variant (ARv567es) from prostate cancer xenografts with exons 5, 6, and 7 deleted, which is constitutively active in prostate cancer cell lines." (PMID 23209612, 2012). "Ribosomal protein S6 kinase (RPS6KA3), which has been implicated in regulating AR activity and prostate cancer cell growth, was identified in this screen, supporting an RNAi screening approach to identify kinases regulating prostate cancer cell growth." (PMID 22761715, 2012). "Conventional wisdom holds that AR mutations are rare in the early phases of prostate cancer and prevalent in AI and metastatic tumors." (PMID 22403669, 2012). "Binding of Foxa1 to its targets was shown to be required for chromatin-association of androgen receptor (AR) in prostate cancer cells, and the estrogen receptor (ER) and retinoic acid receptor (RAR), in breast cancer cell lines." (PMID 22737085, 2012). "Altogether, AI variants illustrated the putative diversity of biological events associated with hormone escape and underlined that an AR-dependent control remains central in prostate cancers." (PMID 22879924, 2012). "We have shown that loss of miR-34a expression in prostate cancer specimens is associated with increased expression of androgen receptor." (PMID 22970379, 2012).
prostate carcinoma (continued). "Androgen-induced AR reprogramming is also observed after downregulation of FoxA1, a pioneer transcription factor involved in AR targeting and frequently mutated in prostate cancer, although the role of FoxA1 in CRPC remains to be determined." (PMID 23019221, 2012). "Oct-1 is a known co-regulator of the androgen receptor, regulates growth of prostate cancer cells and is associated with poor prognosis." (PMID 22970239, 2012). "We discuss the consequences of these findings and the role of androgen receptor mutations for prostate cancer progression and current treatment options." (PMID 22403669, 2012). "Clonal androgen receptor mutations are seen in castrate resistant prostate cancer and appear to be selected for as a mechanism by which prostate cancer cells can survive in low androgen environment." (PMID 22389719, 2012). "The importance of the androgen receptor has been implicated in both normal prostate development and prostate cancer pathogenesis." (PMID 21949845, 2011). "Based on gene microarray studies of seven different human prostate cancer xenograft models, an increase of AR mRNA was the only change consistently associated with the development of the castration-resistant phenotype." (PMID 21859492, 2011). "Clearly, mechanisms for AR amplification and mutation play a role in prostate cancer progression, however, loss of AR has been reported in a subset of hormone-independent cancers, including a complete loss in some cases." (PMID 21966451, 2011). "Conversely, multiple lines of evidence have shown that the length of the AR polyQ tract is inversely correlated with the risk of developing prostate cancer, age of onset, and risk of advanced disease at diagnosis." (PMID 21949845, 2011). "The incidence of somatic mutation in the AR in prostate cancer samples occurs more frequently in tumor cells of distant metastases and recurrent prostate cancer following ADT compared to that seen in primary prostate cancers." (PMID 24212771, 2011). "Different mutations in the AR gene have been identified in various human disorders, including endocrine dysfunctions and prostate cancer." (PMID 21949845, 2011). "Although FKBP5 knockout mice show normal androgen signalling, it has been linked to AR signalling and prostate cancer." (PMID 21119664, 2011). "Genistein also caused androgen receptor (AR) downregulation through inhibition of HDAC6-Hsp90 co-chaperone functions in prostate cancer cells." (PMID 22247744, 2011). "To investigate how the AR pathway is modulated during the development and progression of prostate cancer we linked our androgen-regulated gene signature to seven independent prostate cancer microarray databases." (PMID 21829708, 2011). "These androgen-independent variants of the AR are sufficient to confer castration-resistant growth to prostate cancer cells." (PMID 21513551, 2011). "AR transcriptional activity also drives the onset and progression of prostate cancer (PCa), the second leading cause of male cancer-related deaths with ∼899,000 men diagnosed worldwide each year." (PMID 22194994, 2011). "Understanding the underlying process and complexity of androgen receptor signaling in the progression of castrate-resistant prostate cancer is essential for developing successful therapies of this complex cancer type." (PMID 24213111, 2011). "This pathway has been implicated in the development of CRPC and circumvention of AR involvement in prostate cancer." (PMID 21559022, 2011). "Recent studies have linked AR to EMT in prostate cancer models through the activation of the SNAI axis." (PMID 21747944, 2011). "An analogous case in prostate cancer is the altered target gene spectrum of the androgen receptor caused by changes in the expression of interacting transcription factors like HOXB13 and FOXA1." (PMID 24213107, 2011). "Alternatively, persistent AR activation due to loss-of-function mutations has been reported in some androgen-refractory prostate cancers." (PMID 21241512, 2011).
prostate carcinoma (continued). "Several AR mutations found in prostate cancer tissue have been found to increase the binding affinity to AIB1." (PMID 22033271, 2011). "The conversion of androgen receptor (AR) signaling as a mechanism of growth suppression of normal prostate epithelial cells to that of growth stimulation in prostate cancer cells is often associated with AR mutation, amplification and over-expression." (PMID 20628607, 2010). "Polymorphisms in AR-CAG repeat have been intensively studied as determinant of susceptibility to prostate cancer in Indian population however; its association with breast carcinoma in Indian population is not yet explored." (PMID 20831839, 2010). "Castration-resistant human prostate cancer growth commonly remains AR-dependent and is thought to occur through several mechanisms including AR amplification, AR mutation, changes in AR co-regulators and growth factor activation." (PMID 20585617, 2010). "E006AA cells represent a prototype for a newly identified subtype of prostate cancer cells that exhibit a dominant-negative AR loss-of-function in a hormonally naïve patient." (PMID 20628607, 2010). "Earlier studies have implicated the androgen receptor (AR) in human prostate cancer cells and the progesterone receptor (PR) in breast cancer cells as stimulators of caveolin-1 expression." (PMID 20098621, 2010). "Consistent with these clinical observations, AR gene mutation, amplification and protein over-expression are commonly observed in the majority of prostate cancer cell lines derived from castrate-resistant hosts." (PMID 20628607, 2010). "This review summarises the present data on androgen receptor mutations in prostate cancer, and how such substitutions offer a growth advantage by affecting cofactor interactions or by reducing ligand specificity." (PMID 19721807, 2009). "It is well documented that mutations in the AR allow castration-resistant prostate cancer cells to utilise a broad spectrum of steroids, whose levels are not affected by anti-androgen therapy." (PMID 19337256, 2009). "We used HepG2 cells to allow comparison with an earlier study, and we used LNCaP cells because they contain an AR mutation that is frequently seen in prostate cancer." (PMID 20049203, 2009). "Over 70 different somatic missense AR mutations have been described in patients with prostate cancer." (PMID 19721807, 2009). "Both I3C and DIM caused anti-proliferative effects on prostate cancer cells via AR-mediated pathway." (PMID 19909554, 2009). "Amplification and mutations of AR gene are identified as critical factors related to the poor prognosis of prostate cancer." (PMID 19956729, 2009). "In early stages of prostate cancer mutations of the AR are rare but their frequency is significantly increased in advanced, androgen-independent tumours suggesting that AR mutations play a role in tumour progression." (PMID 19721807, 2009). "Prohibitin has also been linked to human prostate cancer through recent investigations establishing that prohibitin associates with the androgen receptor (AR) and participates in AR-mediated gene regulation." (PMID 21566741, 2008). "Especially important would be the analysis of AR mutations thought to be involved in prostate cancer treatment resistance or AR mutations involved in the androgen resistance observed in AIS." (PMID 18978937, 2008). "The CAG repeat polymorphisms of the androgen receptor gene have been associated with an increased prostate cancer risk and the repeat length has been correlated with cancer stage and grade at presentation." (PMID 18471323, 2008). "Some studies of AR, including ours, found shorter CAG repeats associated with increased expression of AR and with higher risk of advanced prostate cancer compared with longer CAG repeats." (PMID 18827812, 2008).
prostate carcinoma (continued). "There are a number of postulated mechanisms for the development of androgen independence in prostate cancer, including mutations of the androgen receptor to allowing other molecules to bind to it." (PMID 18182976, 2008). "In prostate cancer cell lines, the expression of the androgen receptor and the metastasis associated protein AGR2 has been demonstrated to be decreased by ectopic expression of Ebp1." (PMID 19094237, 2008). "Researchers have found that a decreased repeat length of an AR polymorphism correlates with an increased risk of and aggressiveness of prostate cancer." (PMID 18471323, 2008). "Major efforts have been made in prostate cancer research to understand what role the AR, either amplified wild-type or its different mutated versions, plays in these late-stage prostate cancer cells." (PMID 18218096, 2008). "AR activity has been implicated as pivotal in several phases of prostate cancer: origin, transition to androgen independent status, and progression." (PMID 18471323, 2008). "Studying and understanding of the interaction between VDR and LXR/AR is critical for rational design of future clinical trials with vitamin D compounds for prevention and treatment of associated cancers such as prostate cancer." (PMID 19787078, 2008). "Increased hormone independence in prostate cancer cells was associated with androgen receptor (AR) phosphorylation mediated by transfected HER2." (PMID 17211467, 2007). "In this study, we showed that high doses of PL can mobilize multiple apoptotic signalling pathways to cause different degrees of cytotoxic effects on prostate cancer cells, depending on the expression of AR." (PMID 17262078, 2007). "Our present study indicates that caspase 2 is an intracellular target for upregulating the susceptibility of PC3 cells or prostate cancer cells containing a mutated AR to PL-induced apoptosis." (PMID 17262078, 2007). "Mutations in the AR are uncommon (0-4%) in untreated prostate cancer and those treated with surgical castration." (PMID 19675761, 2007). "In the progression of prostate cancer, AR is often mutated or its expression is lost, which plays an important role in the development of the resistance of cancer cells to treatment." (PMID 17262078, 2007). "Restoration of AR activity is known to occur through several discrete pathways, and in model systems of prostate cancer reactivation of AR is causative for therapeutic relapse and tumour recurrence." (PMID 17375037, 2007). "We show by gene expression analyses that low-level, physiologically relevant and proliferation-inducing doses of BPA and DHT elicit overlapping but distinct transcriptional effects in prostate cancer cells expressing the AR-T877A mutation." (PMID 18007998, 2007). "BPA induces a distinct gene expression signature in prostate cancer cells expressing somatic AR mutation, and a major molecular consequence of BPA action is down-regulation of ERβ." (PMID 18007998, 2007). "Cyclin D1 associates with HDAC3 in prostate cancer cells, through a repressor domain motif that is required and sufficient for AR modulation." (PMID 16863592, 2006). "The study included 190 AR alleles from prostate cancer patients and 186 AR alleles from female control subjects." (PMID 10574254, 1999). "ZMIZ2, an androgen receptor (AR) transcriptional co-regulator, promotes prostate cancer (PCa) cell proliferation by interacting with AR to upregulate genes associated with cell proliferation; however, its specific cooperative mechanisms remain unclear." (PMID 41431399, 2026). "The significant associations observed in prostate cancer pathways suggest that androgen receptor signaling may influence VTE risk by modulating coagulation factor expression, potentially linked to the gender disparities observed clinically." (PMID 41210882, 2025).